AMER1 (APC membrane recruitment protein 1)
Description:
Regulator of the canonical Wnt signaling pathway. Acts by specifically binding phosphatidylinositol 4,5-bisphosphate (PtdIns(4,5)P2), translocating to the cell membrane and interacting with key regulators of the canonical Wnt signaling pathway, such as components of the beta-catenin destruction complex. Acts both as a positive and negative regulator of the Wnt signaling pathway, depending on the context: acts as a positive regulator by promoting LRP6 phosphorylation. Also acts as a negative regulator by acting as a scaffold protein for the beta-catenin destruction complex and promoting stabilization of Axin at the cell membrane. Promotes CTNNB1 ubiquitination and degradation. Involved in kidney development.
Synonyms: FAM123B; WTX; RP11-403E24.2; FLJ39827; OSCS
Tractability: Antibody: its Gene Ontology location is reachable by antibodies, with high confidence; UniProt places it where antibodies can reach, with medium confidence; the Human Protein Atlas places it where antibodies can reach. PROTAC: ubiquitination databases record sites on it.
Gene: Protein-coding gene on chromosome X (64,185,117 to 64,205,708, reverse strand). Ensembl gene ENSG00000184675.
Subcellular location: Cytoplasm; Cell membrane; Nucleus
Subcellular location (Human Protein Atlas): Nuclear bodies; Plasma membrane; Vesicles
Pathways (Reactome):
Disease: APC truncation mutants have impaired AXIN binding; AXIN missense mutants destabilize the destruction complex; CTNNB1 S33 mutants aren't phosphorylated; CTNNB1 S37 mutants aren't phosphorylated; CTNNB1 S45 mutants aren't phosphorylated; CTNNB1 T41 mutants aren't phosphorylated; Deletions in the AMER1 gene destabilize the destruction complex; Signaling by GSK3beta mutants; Truncations of AMER1 destabilize the destruction complex
Signal Transduction: Beta-catenin phosphorylation cascade; Degradation of beta-catenin by the destruction complex; Disassembly of the destruction complex and recruitment of AXIN to the membrane
Cellular responses to stimuli: KEAP1-NFE2L2 pathway
Metabolism of proteins: Neddylation
Gene Ontology:
Molecular function: beta-catenin binding; beta-catenin destruction complex binding; phosphatidylinositol-4,5-bisphosphate binding; protein binding
Biological process: negative regulation of canonical Wnt signaling pathway; positive regulation of canonical Wnt signaling pathway; positive regulation of protein catabolic process; positive regulation of protein ubiquitination; regulation of canonical Wnt signaling pathway
Cellular component: nuclear body; plasma membrane; cytosol; cytoplasm; nucleus
Gene-disease validity (ClinGen):
ClinGen rates the evidence that AMER1 causes each of these diseases.
osteopathia striata with cranial sclerosis (X-linked): Definitive.
Cancer hallmarks: suppression of growth (promotes)
Homologues: Orthologues: macaque AMER1 (96% identical), rabbit AMER1 (87% identical), pig AMER1 (83% identical), dog AMER1 (82% identical), rat Amer1 (79% identical), mouse Amer1 (79% identical), guinea pig AMER1 (77% identical), chimpanzee AMER1 (69% identical), tropical clawed frog amer1 (30% identical), zebrafish amer1 (24% identical). Paralogues in human: AMER2 (14% identical), AMER3 (12% identical).
Diseases named in the same sentence as AMER1 in open-access papers:
AMER1 is named in the same sentence as 33 diseases in open-access papers, as found by Europe PMC text mining. Sharing a sentence is not in itself a finding about the gene and the disease. The quoted sentences say what the papers report.
Wilms tumor (20 papers, 2012 to 2025). An embryonal neoplasm characterized by the presence of epithelial, mesenchymal, and blastema components. "The X-linked gene WTX (also called AMER1) has been reported to function as a tumour suppressor gene in Wilms’ tumour." (PMID 33032635, 2020). "The mechanisms underlying this Wilms tumour predisposition are not known, but it is notable that TRIM28 is a major binding partner of AMER1, which is encoded by a gene that is frequently somatically mutated in Wilms tumour." (PMID 30885698, 2019). "TRIM28 has also been reported to co-immunoprecipitate with AMER1, which is mutated or deleted in 20–30% of Wilms tumours." (PMID 29912901, 2018). "Additionally, AMER1 has been reported to function as a tumor‐suppressor gene in Wilms' tumor, and loss of AMER1 regulates colorectal cancer progression and metastasis." (PMID 38323355, 2024). "APC membrane recruitment protein 1 (AMER1) was first identified as being frequently mutated or deleted in Wilms tumor, a pediatric kidney cancer; hence, it was named Wilms Tumor gene on the X (WTX)." (PMID 39941813, 2025). "Unlike other tumor suppressor genes, APC membrane recruitment 1 (AMER1)/FAM123B/Wilms tumor gene on the X chromosome (WTX) gene is inactivated by a monoallelic “single-hit” event." (PMID 40109379, 2025). "Most of the cases of Wilms tumors with AMER1 (APC Membrane Recruitment Protein 1) alterations have epigenetic abnormalities." (PMID 36295546, 2022). "In primary encapsulated Wilms tumors (HT98 and HT139), deletion of both alleles of AMER1 was detected in both the P0 and respective PDXs." (PMID 36612255, 2022). "Wilms’ tumour gene on the X chromosome (WTX), also known as AMER1 or FAM123B, was the first tumour suppressor gene located on the X chromosome discovered in the Wilms’ tumour." (PMID 33032635, 2020). "APC Membrane Recruitment Protein 1 (AMER1), also known as FAM123B or Wilms tumor on the X chromosome (WTX), is an intracellular inhibitor of the canonical WNT signaling pathway." (PMID 32328030, 2020). "Both APC and CTNNB1 are classic oncogenes, while AMER1 (also known as the Wilms tumor gene on the X chromosome, WTX) is a tumor suppressor gene." (PMID 31781186, 2019). "The tumor suppressor APC employs its conserved armadillo repeat (ARM) domain to recognize many of its binding partners, including Amer1/WTX, which is mutated in Wilms' tumor and bone overgrowth syndrome." (PMID 27462415, 2015). "Amer1/WTX is another important human tumor suppressor whose gene is somatically inactivated in one-third of Wilms' tumors, the most common pediatric kidney cancers." (PMID 27462415, 2015). "And the protein name of WTX (UniProt ID, Q5JTC6) is APC membrane recruitment protein 1 or Wilms tumor gene on the X chromosome protein." (PMID 40109379, 2025). "AMER1/WTX binds to WT1, a zinc-finger transcription factor and also a Wilms tumor suppressor, and enhances WT1-mediated transcription of target genes." (PMID 39941813, 2025).
colorectal cancer (13 papers, 2016 to 2026). A primary or metastatic malignant neoplasm that affects the colon or rectum. "Other exome studies have reported that AMER1 is indeed a frequent target of mutation in colorectal cancer." (PMID 28002797, 2017). "Additionally, we observed that the low-expression group exhibited a high mutational load, with FBXW7, SOX9, AMER1, SMAD4, ARID1A, and B2M being the most frequently mutated genes in colorectal cancer." (PMID 40170839, 2025). "APC membrane recruitment protein 1 (AMER1), another tumor suppressor, facilitates ferroptosis by degrading both SLC7A11 and ferritin light chain in colorectal cancer cells." (PMID 41596341, 2026). "WTX gene also known as AMER1 physically interacts with APC, which is a TSG involved in colorectal cancer." (PMID 38827026, 2024).
gastric cancer (6 papers, 2020 to 2025). A primary or metastatic malignant neoplasm involving the stomach. "It has been reported that IRF2 inhibits cell proliferation by inducing CLDN7 upregulation in oral squamous cell carcinoma, and inhibits cancer proliferation by promoting AMER-1 transcription in human gastric cancer." (PMID 36341357, 2022).
adenoma (4 papers, 2016 to 2025). A neoplasm arising from the epithelium. "MBD4-deficient adenomas harbored fewer KRAS mutations (three of 19 adenomas) than sporadic tumors (Fisher’s exact, p = 0.0028) but significantly more somatic mutations in AMER1 (MIM: 300647) (12 of 19 adenomas; Fisher’s exact, p = 0.039)." (PMID 35460607, 2022). "As expected, we found that APC was the most frequently mutated gene across the adenomas studied, while other WNT pathway genes (CTNNB1, EP300, TCF7L2, and AMER1) were altered less frequently." (PMID 31781186, 2019).
colon adenoma (2 papers, 2017 to 2024). An adenoma that arises from the colon.
colorectal tumors (2 papers, 2017 to 2022). "MBD4-deficient polyps harbored somatic mutations in similar driver genes to sporadic colorectal tumors, although AMER1 mutations were more common and KRAS mutations less frequent." (PMID 35460607, 2022).
cholangiocarcinoma (1 paper, 2022). A carcinoma that arises from the intrahepatic biliary tree (intrahepatic cholangiocarcinoma) or from the junction, or adjacent to the junction, of the right and left hepatic ducts (hilar cholangiocarcinoma). "Nonetheless, the AMER1 protein has never been studied in cholangiocarcinoma and thus was not prioritized for further validation in this study." (PMID 36144640, 2022).
Intellectual disability (1 paper, 2022). "The phenotype of the patient, with linear striations of long bones, cranial sclerosis, hypertelorism, frontal bossing, wide nasal bridge, dental anomalies, hearing loss, and mild intellectual disability, is comparable to the phenotype of patients with constitutional AMER1 mutations and OSCS." (PMID 35991531, 2022).
mesenchymal tumors (1 paper, 2026). "Unlike in mesenchymal tumors, AMER1 mutations in epithelial lineages, including CRC, do not activate the WNT pathway." (PMID 41522471, 2026).
microtia (1 paper, 2024). "In conclusion, the present study identified a gene in zebrafish that was homologous to human AMER1, a candidate gene associated with the pathogenesis of microtia-atresia." (PMID 38255806, 2024). "The AMER1 gene has been identified as potentially pathogenic for microtia-atresia in two twin families." (PMID 38255806, 2024).
osteopathia striata with cranial sclerosis (1 paper, 2022). Osteopathia striata with cranial sclerosis (OS-CS) is a bone dysplasia characterized by longitudinal striations of the metaphyses of the long bones, sclerosis of the craniofacial bones, macrocephaly, cleft palate and hearing loss. "Osteopathia striata with cranial sclerosis (OSCS, OMIM: 300373) is an X‐linked dominant skeletal disorder caused by mutations in the AMER1 gene, encoding the APC membrane recruitment protein 1, which plays a role in the Wnt/β‐catenin pathway." (PMID 35991531, 2022).
pediatric cancer (1 paper, 2024). "The analysis detected mutations in several cancer-related genes previously reported to be implicated in pediatric cancer, such as CTNNB1, WT1, AMER1, and NF1." (PMID 38672648, 2024).
pericardial effusion (1 paper, 2022). Fluid collection within the pericardial sac, usually due to inflammation.
prostate carcinoma (1 paper, 2019). A carcinoma that arises from epithelial cells of the prostate gland. "Mutations in the AMER1 gene are frequently detected in male colorectal cancer, although its status with prostate cancer is uncertain." (PMID 30863497, 2019). "Indeed, a prostate cancer susceptibility locus (loci) has been mapped on Xp11.2 associated with the SNP rs5945572, adjacent of which multiple tumor suppressor genes, including FOXP3 and AMER1 (also known as WTX and FAM123B), are located." (PMID 30863497, 2019).
tumor (31 papers, 2015 to 2026). "No mutations affected oncogenes (defined by COSMIC37,38), and only one potentially damaging mutation affected a tumor suppressor (AMER1 R358Q; observed in one clone)." (PMID 38388848, 2024). "AMER1 (APC Membrane Recruitment Protein 1) is a tumor suppressor mutated in about 10% of CRC patients, especially in tumors with mesenchymal phenotypes linked to canonical Wnt-pathway inhibition." (PMID 31337155, 2019). "Since it has been reported that TRIM28 interacts with AMER1 (WTX) we postulated that tumours with mutations in AMER1 might share common features with TRIM28–mutated tumours." (PMID 29912901, 2018). "Increased expression of IRF-2 can inhibit tumor growth and affect the prognoses of patients by directly regulating AMER-1 transcription in GC and inhibiting the Wnt/β-catenin signaling pathway." (PMID 35115027, 2022). "OS-CS is associated with truncating point mutations or whole gene deletions of WTX (Wilms tumor gene, also known as FAM123B or AMER1), located at Xq11.2." (PMID 36581928, 2022). "AMER-1 has been identified as a tumor suppressor that functions by regulating the Wnt/β-catenin signaling pathway." (PMID 35115027, 2022). "We also found components of the β-catenin destruction complex, namely Axin1 itself and its key binding partner, the APC tumour suppressor, as well as AMER1 and β-catenin, suggesting that the entire complex is associated with Nkd1 HisC aggregates in Wnt-stimulated cells." (PMID 33025907, 2020). "Following unsupervised clustering analysis of genome-wide gene expression the TRIM28 and AMER1-mutated tumours did not cluster together." (PMID 29912901, 2018). "ChIP-Seq assay showed that IRF-2 could directly activate AMER-1 transcription and regulate the Wnt/β-catenin signaling pathway, which was validated using IHC, in both tissue microarray and xenografted tumor tissues, western blot analysis, and cell function experiments." (PMID 35115027, 2022). "Neither of the TRIM28-mutated tumours (37T and W117) had AMER1 mutations." (PMID 29912901, 2018). "The immunohistochemical scores showed positive correlations between AMER-1 and IRF-2 scores, both in TMA specimens (r = 0.58, P < 0.001) and xenografted tumor tissues (r = 0.59, P < 0.001)." (PMID 35115027, 2022). "To further evaluate the relationship between IRF-2 and AMER-1 in GAC patients and xenografted tumor tissues in nude mice, we examined the expression levels of AMER-1 by immunohistochemical assay, using anti-AMER-1 antibody in the same TMA specimens and xenografted tumor tissues." (PMID 35115027, 2022). "Since AMER-1 acts as a scaffold protein that recruits APC to consist of the β-catenin destruction complex, we believe that IRF-2 functions as a tumor suppressor gene in GC and that the axis of IRF-2-AMER-1/β-catenin plays an important role in the phenotype of cell proliferation." (PMID 35115027, 2022). "The expression patterns of AMER1 and TRIM28 mutant tumours did not, however, cluster together, nor did they show similar histological features, suggesting that these two proteins contribute to different tumorigenic pathways." (PMID 29912901, 2018).
cancer (24 papers, 2014 to 2025). A tumor composed of atypical neoplastic, often pleomorphic cells that invade other tissues. "The remaining 45 cancers carry additional truncating mutations in either AXIN1, AXIN2 or AMER1, or defective missense or truncating RNF43 mutations." (PMID 39674817, 2025). "Other mutated cancer genes included those involved in Wnt signaling (APC, AMER1), mitogen signaling (KRAS, BRAF), epigenetic modification (ARID1A, ARID2, DNMT3A, NCOA3) and DNA repair (RAD50, BRIP1, ERCC5, RECQL4)." (PMID 33776923, 2021). "Among pan cancer drivers, EP400 was detected in three individuals, and both synonymous and non-synonymous alterations in the genes AMER1 and PTPRB were detected in two cohort members." (PMID 34016182, 2021). "As an example of the genes involved in cancer, the WTX (or called AMER1, APC membrane recruitment protein 1) has a retained intron with a 3′SS G3 in its second exon." (PMID 25523808, 2014). "In particular, AMER1 negatively regulates Wnt signal transduction by promoting ubiquitination and degradation of β-catenin, while recent data showed that aberrant upregulation of SAM68 induces cancer cell proliferation in vitro by activating the Wnt/β-catenin signaling pathway." (PMID 33670833, 2021). "Of the top 20 genes in TCGA or MSKCC, AMER1, SOX9, ARID1A and TCF7L2 were not included in our cancer panel." (PMID 34074070, 2021).
skeletal dysplasia (1 paper, 2022). Any Mendelian diseases that affects growth and development of the skeleton. "The target next generation sequencing (NGS) analysis of a panel of genes involved in neurodevelopmental disorders and skeletal dysplasias detected a de novo heterozygous mutation of the AMER1 gene, for diagnosis of Osteopathia Striata with Cranial Sclerosis." (PMID 36581928, 2022). "Then, a target next generation sequencing (NGS) analysis, including the genes involved in skeletal dysplasias, was performed and revealed a de novo heterozygous nonsense mutation of the AMER1 gene." (PMID 36581928, 2022).
AMER1 also shares sentences with these, for which no sentence is quoted: colon carcinoma (5 papers); kidney cancer (3); cervical cancer (2); lung adenocarcinoma (2); acute promyelocytic leukemia (1); breast carcinoma (1); colon adenocarcinoma (1); colorectal adenoma (1); endometrial carcinoma (1); epilepsy (1); Familial adenomatous polyposis (1); lymph node metastasis (1); melanoma (1); oral squamous cell carcinoma (1); retinitis pigmentosa (1); Wilms' tumour of the kidney (1).